PI3 (peptidase inhibitor 3)
Description:
Neutrophil and pancreatic elastase-specific inhibitor of skin. It may prevent elastase-mediated tissue proteolysis. Has been shown to inhibit the alpha-4-beta-2/CHRNA2-CHRNB2 nicotinic acetylcholine receptor and to produce a weak inhibition on Kv11.1/KCNH2/ERG1 and on the transient receptor potential cation channel subfamily V member 1 (TRPV1).
Synonyms: ESI; SKALP; WAP3; WFDC14; ELAFIN; cementoin
Tractability: Antibody: its Gene Ontology location is reachable by antibodies, with high confidence; UniProt places it where antibodies can reach, with medium confidence; UniProt predicts a signal peptide or a membrane-spanning region; the Human Protein Atlas places it where antibodies can reach.
Gene: Protein-coding gene on chromosome 20 (45,174,902 to 45,176,544, forward strand). Ensembl gene ENSG00000124102.
Subcellular location: Secreted
Subcellular location (Human Protein Atlas): Plasma membrane; Predicted to be secreted
Pathways (Reactome):
Developmental Biology: Formation of the cornified envelope
Immune System: Antimicrobial peptides
Gene Ontology:
Molecular function: structural constituent of skin epidermis; endopeptidase inhibitor activity; serine-type endopeptidase inhibitor activity; peptidase inhibitor activity
Biological process: cornification; antibacterial humoral response; innate immune response; copulation
Cellular component: cornified envelope; cytosol; extracellular matrix; extracellular region
Genetic constraint (gnomAD): Loss-of-function variants: 4 observed, 6.22 expected, observed/expected ratio (o/e) 0.64, 90% interval 0.31 to 1.45. That is too few expected variants to judge how well the gene tolerates losing a copy. Missense variants: 139 observed, 144.04 expected, observed/expected ratio (o/e) 0.97, 90% interval 0.84 to 1.11. Synonymous variants: 52 observed, 54.59 expected, observed/expected ratio (o/e) 0.95, 90% interval 0.76 to 1.2.
Homologues: Orthologues: chimpanzee PI3 (100% identical), macaque PI3 (93% identical), dog PI3 (66% identical), pig SPAI-2 (52% identical), Drosophila melanogaster CG5639 (25% identical), Caenorhabditis elegans C08G9.2 (22% identical). Paralogues in human: SLPI (33% identical), WFDC12 (26% identical), WFDC5 (26% identical), WFDC3 (20% identical), WFDC13 (15% identical), WFDC9 (15% identical), WFDC10A (14% identical), WFDC11 (14% identical), WFDC10B (13% identical).
Diseases named in the same sentence as PI3 in open-access papers:
PI3 is named in the same sentence as 136 diseases in open-access papers, as found by Europe PMC text mining. Sharing a sentence is not in itself a finding about the gene and the disease. The quoted sentences say what the papers report.
psoriasis (20 papers, 2006 to 2024). An autoimmune condition characterized by red, well-delineated plaques with silvery scales that are usually on the extensor surfaces and scalp. "Moreover, it notably decreased the expression of the genes encoding psoriasis-related cytokine and antimicrobial peptides, which were directly stimulated by the IL-17 pathway (e.g., PI3, DEFB4, IL17C, and TNFA)." (PMID 38951806, 2024). "The expression of psoriasis-related host defence genes PI3 and DEFB433–35 (encoding SKALP/elafin and hBD2, respectively) was increased in both primary and N/TERT keratinocytes, but N/TERT keratinocytes showed a significantly stronger upregulation and this was most pronounced in N/TERT2G cultures." (PMID 28928444, 2017). "CCL20, IL-6, IL-20, IL-17C, and PI3 were previously found to be elevated in patients with psoriasis." (PMID 39224116, 2024). "This analysis revealed the overexpression of SPRR2D, CD52, and PI3 in DCs isolated from psoriasis skin tissues." (PMID 38596682, 2024). "Expression of PI3 is increased in lesional skin and blood from patients with psoriasis and circulating levels of PI3 was shown to correlate with psoriasis disease severity, and is induced by IL-17A in keratinocytes." (PMID 35008981, 2022). "IL-17C and PI3 proteins are also interesting targets that merit further investigation in psoriasis treatment." (PMID 35008981, 2022). "The score of psoriasis area and severity index was positively correlated with the expression of PI3." (PMID 34134787, 2021). "Our data confirmed several proteins already known to be associated with psoriasis, including S100A7, S100A9, beta-defensin 3(DEFB103A), Elafin (PI3), serine protease inhibitors B3, and B4." (PMID 32849499, 2020). "A number of serum analytes identified by Olink analysis, including PI3, IL-17C, CCL20, IL-20, IL-6, CXCL9, and CXCL10, have been previously identified as being elevated in serum samples of patients with psoriasis." (PMID 39224116, 2024). "Compounds with anti-inflammatory activities protect from psoriasis by regulating intracellular ROS and activation of NF-κB, JAK/STAT, and PI3/Akt signaling cascades, as well as immune responses." (PMID 37507888, 2023). "Peptidase inhibitor 3 (PI3), also called skin-derived antileukoproteinase (SKALP) or elafin, is an elastase inhibitor first isolated from skin of patients with psoriasis." (PMID 35008981, 2022). "According to the expression of neutrophil marker genes, skin tissue domain was colored and showed that PI3 and S100A8, two neutrophil marker genes, are highly expressed in psoriasis patients." (PMID 35281792, 2022). "Recapitulating psoriasis skin, IL-17A+TNF-α treatment lead to increased expression of DEFB4, PI3, LCN2, S100A7, and IL36G mRNA over a 72 h time course without marked deterioration of tissue structure." (PMID 30321197, 2018). "In metabolic pathways associated with psoriasis, linoleic acid exhibits a negative correlation with AMPK and the PI3-Akt signaling pathway." (PMID 38529280, 2024). "For example, PI3 was found in the epidermis of patients with psoriasis, but not in normal human epidermis." (PMID 16719916, 2006). "In the presence of PCs, nevertheless, the proliferation rate and number of psoriasis-like cells evidently decreased (P<0.01), accompanied with enhanced HO-1 and antioxidants, and lowered OS/inflammatory indicators as well as phosphorylated JAK2/STAT3/PI3/AKT (P<0.01)." (PMID 36178125, 2022). "The loss of IL-17A/PASI correlation in the presence of atherosclerotic CVD, together with the decreased correlations of PI3, IL-17C, CCL20 and TGF-α with PASI in these patients, clearly merits further investigation and may contribute to further understanding of the links between psoriasis and CVD." (PMID 35008981, 2022). "Although PI3, BD-2, and IL-20 showed the highest correlation with PASI in our dataset, these mediators do not seem to play a central role in psoriasis." (PMID 39224116, 2024).
breast cancer (19 papers, 2009 to 2025). A primary or metastatic malignant neoplasm involving the breast. "High expression of PI3 is significantly associated with poor prognosis of high-grade serous ovarian and breast cancer, and in vitro and in vivo studies have demonstrated that overexpression of PI3 promotes the proliferation of breast cancer." (PMID 38167017, 2024). "For example, GALNT-6 elevated mucin-O-glycosylation of α2M, which activates downstream PI3/Akt signaling pathway, fosters metastasis of breast cancer." (PMID 33889547, 2021). "Upregulation of MALAT1 in breast cancer induces EMT and decreases trastuzumab sensitivity in HER2+ breast cancer, and the mechanism is associated with PI3/Akt-mediated FOXO1 nuclear retention." (PMID 32708561, 2020). "We found in this study that FOXO1 plays a regulatory role in mediating MALAT1 expression in breast cancer cells via the PI3/Akt pathway." (PMID 32708561, 2020). "In ovarian and breast carcinoma, PI3 expression was also found to be transcriptionally up-regulated through activation of the NFκB and MEK/ERK signaling pathway, and correlate with unfavourable overall survival." (PMID 25970782, 2015). "PI3 (Peptidase Inhibitor 3) is a serine protease inhibitor which is involved in breast cancer." (PMID 38167017, 2024). "Furthermore, integrin β1-FAK signaling has not previously been identified to play a role in feedback activation of PI3-AKT signaling mechanisms following MEK suppression in metastatic breast cancer cells." (PMID 27563827, 2016). "However, controversial report has already emerged that PI3 could suppress tumorigenesis through inhibition of elastase and thus could serve as a prognostic indicator in breast cancer." (PMID 25970782, 2015). "The predicted negative scores for PI3/AKT and paxillin signaling pathways correlate well with literature-validated OC anti-invasive activity through downregulating PI3/AKT and paxillin signaling pathways in breast cancer." (PMID 32545325, 2020). "Also, a study has proven that miRNA-511-5p prevents malignant behaviors of breast cancer with a direct effect on SOX9 and PI3/AKT regulatory pathway." (PMID 35322101, 2022). "Besides, abnormal glycosylation has been shown to regulate signaling pathways and markers involved in conservation of CSCs, such as EpCAM glycosylation on cell adhesion and EMT in breast cancer, or N-glycosylation on MAPK and PI3/Akt pathway." (PMID 33889547, 2021). "Gene expression studies of TAMs treated with ruxolitinib showed that mammary tumor cells activate the JAK/STAT pathway in TAMs via secreted soluble factors, and thereby activate several tumor promoting pathways such as the TNF signaling pathway, PI3-Akt signaling pathway, VEGF signaling pathway." (PMID 37005447, 2023).
ovarian carcinoma (19 papers, 2013 to 2025). A malignant neoplasm originating from the surface ovarian epithelium. "Our regression analysis identified six genes significantly associated with ovarian cancer: PI3, TFAP2B, MUC7, PSMA2, PIK3C2G, and NME1." (PMID 41154754, 2025). "On the whole, our study identified five key SRGs, including the risk genes AUP1, PI3 and CCDC80, as well as the protective genes CD200 and GNAS and elucidated their prognostic potential in ovarian cancer." (PMID 40534859, 2025). "Through single-cell analysis, we further identified five potential prognostic biomarkers associated with the ovarian cancer cell functional pathway and TIME: three risk genes PI3, AUP1 and CCDC80 and two protective genes CD200 and GNAS." (PMID 40534859, 2025). "Through integrated machine learning and single-cell analysis, we identified five prognostic-associated SRGs (PI3, AUP1, CD200, GNAS and CCDC80) regulated by global SUMOylation levels in ovarian cancer." (PMID 40534859, 2025). "Recent studies identified PI3 as a biomarker of poor outcome of ovarian cancer and indicated recurrence." (PMID 33819196, 2021). "The PI3-AKT/AKT pathway is activated in 40% of ovarian cancers, and this activation is correlated with a poor prognosis." (PMID 31213009, 2019). "According to recent studies, the overexpression of PI3 in ovarian cancer cells resulted in them gaining resistance against chemotherapeutic drugs-induced apoptosis." (PMID 31404090, 2019). "We previously demonstrated that C6 ceramide and paclitaxel function synergistically to induce ovarian cancer cell death via modulation of the PI3/AKT cell survival pathway." (PMID 23833655, 2013). "Previously, an inhibitory role of PI3 in cisplatin-induced apoptosis has been reported in ovarian cancer cells, whereas SLPI inhibited TNFα-induced apoptosis in lymphoma-derived U937 cells; however, a role for apoptosis regulation in brain tumors has not been addressed before." (PMID 37158962, 2023). "Therefore, it is possible that survivin-mediated EMT may occur through the TGFβ, ERK1/2, and PI3/AKT pathways in ovarian cancer cells." (PMID 29212257, 2017). "CADM1 overexpression potentially inhibits the migration and invasion of ovarian cancer cells by regulating the upstream regulatory factor C4b-binding protein (C4BPA) and the PI3/Akt/mTOR signaling pathway." (PMID 38481252, 2024). "We found that the expression intensity and quantity of PI3, RGS1, PTGER3 and CCDC80 in ovarian cancer tissue was higher than that in normal ovarian tissue." (PMID 33271935, 2020). "TGFβ1 was reported to upregulate TG2 in ovarian cancer by upregulating the activity of NFκB and via the ERK and PI3/AKT pathway in diseased pulmonary fibroblast." (PMID 28223538, 2017). "And it indicated that single gene expression of IDO1, PI3 and TRIM22 could influence the chemotherapy sensitivity of ovarian cancer patients." (PMID 34736480, 2021). "The results showed that they could better predict the sensitivity of ovarian cancer patients to chemotherapeutic drugs than which based on single gene like IDO1, PI3 and TRIM22." (PMID 34736480, 2021). "The concurrent activation of multiple signaling pathways, including EGFR, PI3/AKT, MEK/ERK and JAK/STAT3, appears to be more common in ovarian cancer and raises an important question about the involvement of these signaling pathways in the development of drug resistance." (PMID 25928246, 2015). "Activin A, a member of the TGFβ superfamily present in the follicular fluid released during ovulation, induced EMT and stimulated migration of fallopian tube epithelium cells and HGS ovarian cancer cells by activation of the non-canonical PI3/AKT and MEK/ERK pathways." (PMID 31213009, 2019). "Thus, the scoring model based on the gene expressions of CXCL13, IDO1, PI3, SPP1 and TRIM22 from GSE15622 dataset and constructed by lasso algorithm could better predict the sensitivity of ovarian cancer patients to chemotherapeutic drugs than which based on single gene." (PMID 34736480, 2021).
gastric cancer (16 papers, 2012 to 2025). A primary or metastatic malignant neoplasm involving the stomach. "BMP2 causes the invasion and proliferation of gastric cancer cells through the activated PI3/Akt signalling pathway." (PMID 38627856, 2024). "Tumor cell regions were demarcated using gastric cancer-specific marker genes (KRT17/PRAME/GNGT1/GJB5/PI3)." (PMID 40452847, 2025). "PI3 has antibacterial and anti-inflammatory properties, and it has been proposed as a biomarker for gastric cancer chemotherapy prediction." (PMID 41010012, 2025). "The role of drugs that target the PI3/Akt/m-TOR pathway is to restore the effectivity of chemotherapy against gastric cancer cells by inhibiting cell proliferation and supporting apoptosis." (PMID 30271341, 2018). "In the pancreatic and gastric cancers, the most evaluated pathways were PI3 and MAPK." (PMID 33127962, 2020). "Moreover, a recent study indicated that its downregulation may promote the development of gastric cancer by affecting cell proliferation and migration, as well as activation of the PI3/Akt/mTOR signaling pathway." (PMID 30185791, 2018). "Using the top eight upregulated genes (SLPI, PLA2G2A, CXCL1, CCL20, REG1A, CLDN7, PI3, LGALS3) as a representative gene set for the high metabolic subcluster, we calculated the GSVA score of this gene set for each patient in the TCGA gastric cancer cohort." (PMID 38831933, 2024). "EGF can promote Ataxin-2-like (ATXN2L) as a stress granule regulator in the PI3/AKT signaling pathway, leading to oxaliplatin resistance and eventually increased cell invasion in gastric cancer." (PMID 35004322, 2021). "On the other hand, increased invasion of gastric cancer cells can occur in response to oxaliplatin through ATXN2L up-regulation, known as the regulator of SGs, with the effect of EGF along with the PI3 / AKT signaling pathway." (PMID 34604242, 2021). "For example, tRF-5026a was shown to regulate PTEN/PI3/AKT signaling pathway and decrease gastric cancer cell proliferation, suggesting that tRF-5026 may be used as a biomarker for gastric cancer." (PMID 35721477, 2022). "In addition, a recent study suggested the role of PI3/Akt and ERK pathways in the PAK4-induced cisplatin resistance in gastric cancer cells." (PMID 25238288, 2014). "PI3 (peptidase inhibitor 3, skin-derived (SKALP)) gene, amplified in the 20q12-q13.2 region, displayed the strongest copy number amplification correlated overexpression in gastric cancer." (PMID 22559327, 2012).
melanoma (9 papers, 2013 to 2025). A malignant, usually aggressive tumor composed of atypical, neoplastic melanocytes. "The direct roles of desmoplakin (DSP) and peptidase inhibitor 3 (PI3) in melanoma metastasis are largely limited, though they are generally involved in cell-cell adhesion." (PMID 40722520, 2025). "PI3 induces apoptosis in melanoma cells by intrinsic apoptotic pathway, and suppression of PI3 in melanoma leads to disease progression." (PMID 35984577, 2022). "Though PI3 interacts with progesterone, its relevance as an anti-cancer agent in melanoma remains unclear." (PMID 40722520, 2025). "Other studies exploring dual inhibition of the MAPK and the PI3K-AKT pathway using a different panel of inhibitors also found that combinations of MAPK and PI3-AKT pathway inhibitors augment induction of apoptosis in melanoma cells compared to single drug treatments." (PMID 24735930, 2014).
glioma (8 papers, 2008 to 2025). A benign or malignant brain and spinal cord tumor that arises from glial cells (astrocytes, oligodendrocytes, ependymal cells). "For example, circ-0014359 targeted miR-153 to regulate the PI3 signaling pathway to promote glioma development and circ_0034642 contributed to glioma cell proliferation by elevating the BATF3 expression through serving as a miR-1205 inhibitor." (PMID 34057019, 2021). "Our results demonstrate that MMP-2-depleted-CM abrogated IR-induced SDF-1/CXCR4 expression and PI3/AKT-mediated angiogenesis in glioma xenograft cells." (PMID 23381805, 2013). "Signal transducer and activator of transcription-3 (Stat3) was studied along with several steps of the PI3/Akt pathway in a series of 64 gliomas that included both malignant and low-grade tumors, using quantitative immunohistochemistry, Western blotting, and molecular biology techniques." (PMID 19421400, 2008). "Among these, the top 15 pathways included those involved in prion disease, infections (Hepatitis B, HTLV-1), PI3-AKT signaling pathway, viral carcinogenesis, and specific type of cancers including colorectal cancer, pancreatic cancer and glioma." (PMID 25807141, 2015). "We wanted to assess whether GRM3 stimulation by receptor specific agonists in glioma cells could activate two well-known cell proliferation pathways, the MAPK and PI3/AKT pathways." (PMID 31073373, 2019). "This study demonstrates that antagonizing apoptosis-resistance pathways, such as the PI3/Akt pathway, in combination with death receptor activation, may induce cell death in TRAIL-resistant glioma." (PMID 26044191, 2015).